THRB (thyroid hormone receptor beta)
Diseases named in the same sentence as THRB in open-access papers (continued):
Sharing a sentence is not in itself a finding about the gene and the disease.
hypothyroidism (14 papers, 2012 to 2025). Abnormally low levels of thyroid hormone. "We report the case of a 50-year-old Caucasian female with a confirmed variant c.1357C > A, p.P453T mutation in the THRβ gene, presenting with recurrent goitre, hypothyroidism, and progressive cardiovascular complications." (PMID 40761432, 2025). "The THRB K146Q mutation altered the recruitment of transcription factors to the TSHβ gene promoter, compared with WT, in hyperthyroidism and hypothyroidism." (PMID 34237030, 2021). "Hypothyroidism and mutations in the thyroid hormone receptor β gene (THRB) have been linked to hearing loss." (PMID 34957108, 2021). "Both hypothyroidism and mutation of the thyroid hormone receptor β (THRB) gene delay the onset of GER remodeling and result in subsequent hearing loss." (PMID 34957108, 2021). "THRA and THRB mutations directly caused abnormal thyroid hormone levels, which was associated with tissue-specific hypothyroidism." (PMID 33959028, 2021). "Thus, THRB-linked processes and the association between hypothyroidism and NRAS-mutant melanoma should be further experimentally validated, as thyroid hormone therapy might be a novel strategy for NRAS-mutant melanoma treatment." (PMID 25537510, 2015). "Finally, inactivating mutations of the thyroid hormone (TH) receptor genes THRA and THRB or the TH transmembrane transporter gene MCT8 result in peripheral hypothyroidism due to a reduced sensitivity of target tissues to TH." (PMID 36983233, 2023). "Hence, the active compouds of AMR have direct interaction with THRA and THRB targets, and up-regulated the T3 and T4 levels to alleviate hypothyroidism." (PMID 33959028, 2021). "Meanwhile, the results of network pharmacology indicated that THRA and THRB might be potential therapeutic targets for hypothyroidism." (PMID 33959028, 2021). "We reported for the first time that the thyroid hormone receptor beta (TRβ) decreased significantly in diabetic rats, which was different from hypothyroidism with elevated levels of TR, suggesting that alterations of thyroid hormone receptors could help identify hypothyroidism and NTIS in diabetics." (PMID 29984235, 2018). "Finally, differential expression of one of the thyroid hormone receptors, THRB, may correlate with the high prevalence of hypothyroidism in patients with cutaneous melanoma." (PMID 25537510, 2015). "While our results revealed that both the fetal LVR and KID express THRA and THRB, gene expression of IGFBPs in the fetal LVR was much more perturbed by the impact of fetal hypothyroidism." (PMID 40693299, 2025). "For the second case, the THRB gene mutation of the second case (Chromosome site: Chr 3:24 164404; exon site: 12 c.1357 C > G) had typical RTH manifestations without any significant performance of thyrotoxicosis or hypothyroidism." (PMID 33751836, 2021).
breast cancer (13 papers, 2013 to 2025). A primary or metastatic malignant neoplasm involving the breast. "More recently, high levels of the thyroid hormone receptor beta in breast tumors were also associated with increased breast cancer-specific survival." (PMID 32807826, 2020). "Interestingly, 22% of sporadic breast cancers stained positive for THRβ, while a much higher proportion (53%) of the BRCA1-mutated tumors stained positive for THRβ." (PMID 38785457, 2024). "Furthermore, high levels of THRB are associated with a better outcome in breast cancer." (PMID 34945824, 2021). "In vivo animal investigations revealed that STAT4 overexpression reversed breast cancer cells’ resistance to radiation and decreased tumour development via increasing THRB expression." (PMID 41010015, 2025). "Similarly, 38% of breast cancer patients showed high protein levels of THRB." (PMID 34945824, 2021). "In the current study, we used MCF-7 breast cancer cell line to determine the effect of EFA-CLA, as potential ligands for peroxisome proliferator-activated receptors (PPARs), on identified in silico PPAR-responsive genes: BCAR3, TCF20, WT1, ZNF621, and THRB (transcript TRβ2)." (PMID 28458685, 2017). "Similarly, we expanded the breast cancer input layer with the hyaluronan-mediated motility receptor (HMMR) connected to FN1; the TGFBR connected to SNAI1 and SNAI2; the interLeukin 1 receptor type I (IL1R1) and the thyroid hormone receptor beta (THRB) connected to TRAF1 and MYC, respectively." (PMID 28775339, 2017).
hyperthyroidism (11 papers, 2014 to 2025). Overactivity of the thyroid gland resulting in overproduction of thyroid hormone and increased metabolic rate. "Heterozygous THRB gene mutations cause hyperthyroidism due to thyroid hormone resistance (OMIM ID:188750)." (PMID 39992598, 2025). "A case with hyperthyroidism had a heterozygous pathogenic variant in THRB gene which encodes thyroid hormone receptor protein." (PMID 39992598, 2025). "•Mutations in the thyroid hormone receptor beta (THRB) lead to relative hyperthyroidism in the brain." (PMID 32217468, 2020). "THRB gene mutations are related to a tendency towards thrombosis in patients with hyperthyroidism." (PMID 37876543, 2023). "Evidence suggests that the procoagulant effect observed in hyperthyroidism is mediated through the thyroid hormone receptor beta gene (THRB) and hypofibrinolysis due to it." (PMID 39188469, 2024). "The fact that the other family members manifested no symptoms of hyperthyroidism or mutations in THRβ gene further confirmed the proband's diagnosis of PRTH." (PMID 27537566, 2016). "The drug’s selectivity for the target receptor is crucial to mitigate the levothyroxine-induced issue of binding to both THRα and THRβ, which would otherwise lead to hyperthyroidism in non-target tissues." (PMID 40217851, 2025).
Obesity (11 papers, 2018 to 2025). Accumulation of substantial excess body fat. "In recent years, TH analogs that selectively bind to THRβ have gained attention as new agents for treating dyslipidemia and obesity, which continue to pose major challenges to public health worldwide." (PMID 39107484, 2024). "Our findings suggest that obesity may alter expression of THRB and DIO3 genes through epigenetic mechanism." (PMID 36320063, 2022). "Bioinformatics analysis indicated that THRB was significantly downregulated in obese patients with NAFLD, and this phenotypic change was validated in an animal model with obesity." (PMID 36300106, 2022).
thyroid hormone resistance (9 papers, 2015 to 2025). "This case report describes a patient with thyroid hormone resistance due to a heterozygous mutation in the THRB gene." (PMID 39958082, 2025). "Mutations in THRB cause generalized thyroid hormone resistance in human and a recent CRISPR study in zebrafish revealed its function in photoreceptor development." (PMID 33274714, 2020). "Given the unique nature and scaffold of roxadustat as a THRβ-selective ligand, we next investigated its ability in activating THRβ associated with thyroid hormone resistance." (PMID 31655060, 2019). "Thyroid hormone resistance is most commonly found in THRB gene mutations and more rarely in THRA mutations; in some cases both genes are unchanged (non-TR RTH)." (PMID 25908941, 2015). "The role of THRB in the mediation of biological activities of THs may be gleaned from evidence showing that mutations in the human THRB result in generalized thyroid hormone resistance (GTHR) and the elevation of circulating TH levels." (PMID 30406127, 2018). "Furthermore, the mutation of THRB was reported to be significantly associated with thyroid hormone resistance (THR)." (PMID 30419816, 2018).
papillary thyroid carcinoma (8 papers, 2014 to 2025). "We report for the first time that increased expression of miR146-a, a microRNA that has been experimentally shown to bind and degrade THRB mRNA in papillary thyroid carcinoma, is associated with the loss of THRB expression in endometrial carcinomas." (PMID 32894083, 2020). "First, studies in papillary thyroid carcinoma and renal cell carcinoma have both shown that microRNAs downregulate expression of THRB, and that other molecular modifications, such as promoter methylation, are less involved in regulating THRB expression." (PMID 32894083, 2020). "Previous studies have established relationships between increased miRNA expression and decreased THRB mRNA expression in papillary thyroid carcinoma and in renal cell carcinoma." (PMID 32894083, 2020). "The miRNA with the most significant q-value, miRNA-146a, was shown in a previous study to directly interact with THRB mRNA in papillary thyroid carcinoma." (PMID 32894083, 2020). "The potential role of microRNA-dependent regulation in THRB silencing was suggested for ccRCC and proven for papillary thyroid carcinoma." (PMID 24849932, 2014). "Recent studies have provided evidence that the expression of the THRB gene could also be repressed through a microRNA regulatory mechanism in papillary thyroid carcinoma." (PMID 25924236, 2015).
dyslipidemia (7 papers, 2021 to 2025). "Indeed, in the last few decades, the drug-targetable property of THRs has been utilized to develop different THRβ selective modulators to treat primarily lipid-related metabolic disorders, including dyslipidemia and non-alcoholic fatty liver disease/non-alcoholic steatohepatitis (NAFLD/NASH)." (PMID 40277905, 2025).
endometrial cancer (5 papers, 2020 to 2025). Primary or metastatic malignant neoplasm involving the endometrium (mucous membrane that lines the endometrial cavity). "Applying the receptLoss algorithm, the authors highlighted that loss of THRB gene expression was linked to favorable prognosis in endometrial cancer." (PMID 35269838, 2022). "Tumours with THRB expression loss were noted to be enriched with microsatellite instable molecular subtypes of endometrial cancer." (PMID 34771605, 2021). "The previously unreported association between loss of THRB expression and microsatellite instability in endometrial carcinoma forms the basis for future mechanistic studies and links THRB expression loss to a molecular subtype established by TCGA." (PMID 32894083, 2020). "We report, for the first time, that THRB expression is lost in a subset of endometrial carcinomas and is associated with poorer 5-year survival." (PMID 32894083, 2020). "This assumption may be supported by a previous published study that THRB gene loss expression in women with endometrial cancer and integrin αvβ3 is overexpressed in ovarian cancer." (PMID 38253698, 2024). "In addition, a novel association between thyroid receptor beta (THRB) expression loss and improved 5-year survival in endometrial carcinoma is described." (PMID 32894083, 2020). "The previously unreported observation that THRB is lost in a subset of endometrial cancers and is associated with better 5-year survival could aid in the development of prognostic biomarkers and of targeted therapeutic regimens for endometrial carcinoma that modulate thyroid receptor signaling." (PMID 32894083, 2020). "The elevated expression of miRNA-146a in tumors that lose THRB expression suggests a potential biological mechanism through which THRB expression is lost in endometrial cancer." (PMID 32894083, 2020). "The application of receptLoss to endometrial cancer gene expression data identified THRB, a previously undescribed biomarker of survival in endometrial cancer." (PMID 32894083, 2020). "Pique and colleagues applied a novel computational tool, receptLoss, to gene expression data from The CancerGenome Atlas (TCGA) and found an association between thyroid hormone receptor beta (THRB) expression loss and increased five-year survival in women with endometrial cancer." (PMID 34771605, 2021). "The mechanisms by which THRB expression is lost in endometrial cancer remain under investigation." (PMID 32894083, 2020). "However, further studies are warranted to conclusively determine the relationship between miR146-a and THRB expression in endometrial cancer." (PMID 32894083, 2020). "To date, the expression of THRB in endometrial carcinoma has not been characterized." (PMID 32894083, 2020).
fibrosis (5 papers, 2023 to 2025). the formation of excess fibrous connective tissue in an organ or tissue in a reparative or reactive process. "Using this cutpoint on histologically low-risk samples with F0 and F1 fibrosis, THRB regulon activity identified a subset of MASLD patients with high risk of hepatic decompensation." (PMID 37903863, 2023). "Resmetirom, a thyroid hormone receptor beta (THR-β) agonist, is the first approved therapy for steatohepatitis with fibrosis, yet improves histology in only 25–30% of patients." (PMID 41295331, 2025). "Resmetirom, a thyroid hormone receptor beta (THR-β) agonist, was recently approved by the United States Food and Drug Administration (FDA) for MASH treatment, but only for patients with F2/F3 fibrosis." (PMID 40225300, 2025).
Hypercholesterolemia (5 papers, 2020 to 2025). An increased concentration of cholesterol in the blood. "In fact, THRβ is mainly expressed in the liver, which initially led to the development of THRβ agonists to treat hypercholesterolemia." (PMID 37628929, 2023).
ovarian carcinoma (5 papers, 2012 to 2025). A malignant neoplasm originating from the surface ovarian epithelium. "THRB is associated with prognosis in various cancer entities and has been used in previous studies as a prognostic marker in cancers such as lung adenocarcinoma, high-grade plasmacytoma, ovarian cancer, and colorectal cancer." (PMID 40869909, 2025). "A set of eight biomarkers: NKIRAS1/RPL15, THRB, RBPS3 (CTDSPL), IQSEC1, NBEAL2, ZIC4, LOC285205 and FOXP1, was identified as the most prominent set capable to detect both early and late stages of ovarian cancer." (PMID 23202957, 2012).
steatosis (5 papers, 2021 to 2025). Increased lipid within the cytoplasm of cells. "Cell-based assays confirm that THRB activation mitigates lipid and cholesterol build-up, underscoring its protective role against steatosis." (PMID 40603776, 2024). "In the liver, high TH action protects against steatosis by enhancing cholesterol and triglyceride turnover, with thyroid hormone receptor beta (THRB) signaling playing a pivotal role." (PMID 40603776, 2024). "THRβ mutation mice with a dominant negative effect on THRβ genes will develop hepatocyte steatosis, which indicates the role of THRβ; this phenomenon is attributed to decreased THR-mediated fatty acid β-oxidation and increased PPARγ signaling." (PMID 36296646, 2022). "For instance, resmetirom, a thyroid hormone receptor beta-selective agonist that recently received conditional FDA approval, exhibited a reduction of 35–46% in steatosis, as assessed by MRI-PDFF." (PMID 41334457, 2025). "To directly assess the role of hepatic THRB action in the regulation of steatosis, we treated AML12 hepatocytes with palmitate with or without pharmacological activation of THRB." (PMID 40603776, 2024). "While the expression of other candidates, including RORA, RORC, and THRB, remained unchanged, that of PPARA significantly decreased as NAFLD progressed to steatosis and NASH, and showed a negative correlation with that of MIR20B." (PMID 34964438, 2021).
thyroid hormone resistance syndrome (5 papers, 2014 to 2026). An inherited autosomal recessive trait, characterized by peripheral resistance to thyroid hormones and the resulting elevation in serum levels of thyroxine and triiodothyronine. "There has been an association of follicular thyroid cancer (FTC) in mouse models with some specific thyroid hormone receptor beta (THRB) mutations which can cause thyroid hormone resistance syndrome." (PMID 40535346, 2025). "Moreover, thyroid hormone resistance syndrome is mainly caused by the mutated THRB gene." (PMID 40535346, 2025). "Therefore, thyroid hormone resistance syndrome caused by THRB mutation (RTHβ) was diagnosed." (PMID 30693116, 2018).
atrial fibrillation (4 papers, 2022 to 2025). A disorder characterized by an electrocardiographic finding of a supraventricular arrhythmia characterized by the replacement of consistent P waves by rapid oscillations or fibrillatory waves that vary in size, shape and timing and are accompanied by an irregular ventricular response. "For example, a locus associated with atrial fibrillation and heel bone mineral density is linked to thyroid hormone receptor beta (THRB) - one of several receptors for thyroid hormones - in cluster 1307." (PMID 37749083, 2023). "The proband developed atrial fibrillation and life-threatening heart failure with pulmonary edema, which was quite different from previously reported THRβ gene mutations." (PMID 36499571, 2022). "Variants in THRB are linked to various phenotypes, including cognitive function, asthma, telomere length, myopia, and atrial fibrillation." (PMID 40502754, 2025). "A recent study conducted in 61 individuals with genetically confirmed THRB mutations showed increased risks for all-cause mortality [hazard ratio (HR) 2.84], atrial fibrillation (HR 10.56), heart failure (HR 6.35), and major adverse cardiovascular events (HR 3.49) compared to controls." (PMID 39189533, 2025).
liver disease (4 papers, 2020 to 2026). "Since employing PHH may be resource-prohibitive for many researchers, hepatocellular carcinoma (HCC) cell lines that express more THRB than THRA, such as Huh-7 cells, are suitable alternatives and have been routinely used as in vitro models for liver diseases such as NAFLD." (PMID 33306682, 2020).
Non-Alcoholic Fatty Liver Disease (4 papers, 2021 to 2025). "Activation of thyroid hormone receptor β (THRβ) has shown beneficial effects on metabolic alterations, including non-alcoholic fatty liver disease (NAFLD)." (PMID 34884910, 2021). "In summary, YWS01125, a pyridazinone compound which we newly designed and synthesized, as an effective target, exhibited excellent activity targeting THRβ, and we studied its pharmacokinetics in vivo and found that it is a potential drug for the treatment of nonalcoholic fatty liver disease." (PMID 35620649, 2022).
adenoma (3 papers, 2014 to 2021). A neoplasm arising from the epithelium. "Somatic mutation has been described in TRβ (THRB) and a patient with TSHoma and germline THRB mutation, corresponding to data from a THRB-deficiency animal model where TSH-secreting adenomas have been observed." (PMID 33543431, 2021).
breast tumors (3 papers, 2011 to 2020). "Reports of decreased THRβ expression in breast tumours relative to normal tissue, which was also observed in the current study, and THRβ1 suppression of tumour invasiveness and metastasis suggest an anti-tumour role for THRβ." (PMID 21283523, 2011).
colorectal cancer (3 papers, 2023 to 2025). A primary or metastatic malignant neoplasm that affects the colon or rectum. "To identify the molecular mechanism underlying the ETV4-mediated EMT and metastasis in colorectal cancer cells, we next leveraged our RNA-seq data and a series of key downstream genes associated with EMT were further confirmed, including MER3, MSX1, LOXL2, THRB, WISP2, COL11A1, ADRB2 and E2F2." (PMID 41281746, 2025). "Also, a study on 59 colorectal carcinomas reported a significant overexpression of THRα1 in advanced-stage cancers compared to early-stage cancers, similar to what we observed in ATC cells, that markedly upregulate THRα compared to nontumoral thyroid cells while inhibiting the THRβ transcription." (PMID 36877008, 2023).
follicular thyroid cancer (3 papers, 2021 to 2025). "Indeed, exogenous expression of THRB in human follicular thyroid cancer (FTC) cells (FTC-133 and FTC-236) reduced cell proliferation and impaired cell migration through inhibition of the PI3K-AKT-mTOR pathway." (PMID 34761120, 2021).
hepatocellular carcinoma (3 papers, 2020). A malignant tumor that arises from hepatocytes. "Indeed, modulating thyroid hormone receptor beta signaling has been investigated successfully as a therapeutic strategy in murine models of hepatocellular carcinoma." (PMID 32894083, 2020).